GHRHR (growth hormone releasing hormone receptor)
Diseases named in the same sentence as GHRHR in open-access papers:
GHRHR is named in the same sentence as 96 diseases in open-access papers, as found by Europe PMC text mining. Sharing a sentence is not in itself a finding about the gene and the disease. The quoted sentences say what the papers report.
dwarfism (7 papers, 2009 to 2025). "Malfunction in GHRHR signaling is associated with abnormal growth, making GHRHR an attractive therapeutic target against dwarfism (e.g., isolated growth hormone deficiency, IGHD), gigantism, lipodystrophy and certain cancers." (PMID 33060564, 2020). "Patients with GHRHR mutations have marked dwarfism transmitted in a recessive fashion, and are phenotypically and biochemically indistinguishable from other forms of IGHD." (PMID 21274317, 2010). "Patients with growth hormone releasing hormone receptor (GHRHR) mutations exhibit pronounced dwarfism and are phenotypically and biochemically indistinguishable from other forms of isolated growth hormone deficiency (IGHD)." (PMID 21274317, 2010). "Single SNPs and haplotypes in the GHRHR gene region have also been reported to be associated with normal short (not dwarfism) or tall stature, but these findings were not replicated in either of two independent population samples." (PMID 19209235, 2009). "Another example is the dwarfism of Itabaianinha, which we first described in 1999 in the northeasterner Brazilian state of Sergipe, characterized by severe IGHD due to the c.57 + 1G> A mutation in the GHRH receptor gene (GHRHR, OMIM No. 612781)." (PMID 34118183, 2021).
prostate carcinoma (5 papers, 2008 to 2024). A carcinoma that arises from epithelial cells of the prostate gland. "GHRH-induced cAMP responses were subsequently measured in three prostate cancer cell lines expressing different levels of GHRHR and SV1." (PMID 34599099, 2021). "However, the level of GHRHR SV1 mRNA in SKOV3 and CaOV3 cells is lower than that in LNCaP prostate cancer cells, which were used as a positive control." (PMID 20509930, 2010).
androgen excess (3 papers, 2019 to 2022). "Thus, hypomethylation and overexpression of GHRHR observed in CGCs can be an indirect mediator of androgen excess in PCOS." (PMID 30975191, 2019). "CpG hypomethylation in genes such as AKR1C3, GHRHR, MAMLD1 and RETN, and hypermethylation in TNF, which can indirectly contribute to androgen excess, were consistent with increased and decreased levels of the respective gene transcripts." (PMID 30975191, 2019). "Recent research has shown that CpG hypomethylation regarding GHRHR, AKR1C3, RETN, and MAMLD1 and hypermethylation regarding TNF, which can indirectly contribute to androgen excess, were consistent with increased and decreased levels of the corresponding gene transcripts, respectively." (PMID 33763111, 2021).
diabetes (3 papers, 2016 to 2025). "Previous studies have demonstrated the therapeutic potential of the GHRHR agonist MR409 in experimental models of diabetes." (PMID 40926987, 2025). "This review addresses the possible role of GHRHR and its unique engineered agonists and antagonists for treating diabetes and its complications." (PMID 27777568, 2016). "We believe that there is a sound basis for further studies evaluating GHRHR agonists and/or antagonists as promising therapeutic agents for diabetes and its complications." (PMID 27777568, 2016). "Additional expression of the major antioxidant enzymes may have additional benefits in T2DM as well as T1D, and this may be another potentially beneficial effect of GHRHR agonists in both major types of diabetes." (PMID 27777568, 2016). "On the other hand, the modulators of GHRHR activity may be useful in ameliorating certain complications of diabetes." (PMID 27777568, 2016). "GHRHR antagonists may target certain complications of diabetes, especially in Type 1 diabetes and insulin-dependent T2DM, where insulin production by the beta-cell is at least clinically insignificant." (PMID 27777568, 2016). "Decreased glucagon release by GHRHR antagonists could have a beneficial effect in diabetes through decreasing hepatic glucose production and perhaps decreasing ketogenesis." (PMID 27777568, 2016). "Cross-talk between the GHRHR antagonist and acetylcholine signaling (M3 receptor) was observed in the aorta, where MIA-602 prevented the diabetes-related block of carbachol-mediated vasodilation." (PMID 27777568, 2016). "This review considers the role of GHRHR in the beta-cell and addresses the unique engineered GHRH agonists and antagonists for treatment of type 2 diabetes mellitus." (PMID 27777568, 2016). "Treatment with the GHRHR antagonist, MIA-602, interfered with GLP-1-dependent diabetes-related dyslipidemia in mice." (PMID 27777568, 2016).
gastric cancer (3 papers, 2018 to 2023). A primary or metastatic malignant neoplasm involving the stomach. "For example, the growth hormone-releasing hormone receptor (GHRH-R) can promote human gastric cancer via PAK1-NF-κB signaling." (PMID 32863957, 2020).
melanoma (3 papers, 2017 to 2023). A malignant, usually aggressive tumor composed of atypical, neoplastic melanocytes. "Then, we identified 9 LR pairs (“BMP6- > HJV” 、"CCL8- > ACKR4” 、"DLL3- > NOTCH3"、"DSC3- > DSG3"、"GHRH- > GHRHR” 、"LRRC4B- > PTPRF"、"SEMA4D- > PLXNB1"、"SFRP1- > FZD6"、"UCN- > CRHR1′′) as key LR pairs in melanoma prognosis through Lasso Cox regression and Multiple Stepwise Regression." (PMID 36777724, 2023). "And its receptor, GHRHR, is related to the pathogenesis of melanoma." (PMID 36777724, 2023). "Moreover, primary human melanoma specimens were even found to have high levels of GH releasing hormone (GHRH) receptor (GHRHR), while GHRH-analogs were successful in suppressing malignant melanoma growth in vivo." (PMID 28223541, 2017). "Furthermore, in primary human melanoma samples, an elevated expression of the GH-releasing hormone receptor (GHRH) (GHRHR) has been demonstrated, while GHRH analogues have been shown to suppress the growth of malignant melanomas in vivo." (PMID 35160191, 2022).
ovarian carcinoma (3 papers, 2010 to 2024). A malignant neoplasm originating from the surface ovarian epithelium. "The GHRHR has recentlybeen highlighted as a promising drug target toward several types ofcancer and has been shown to be overexpressed in prostate, breast,pancreatic, and ovarian cancer." (PMID 39207455, 2024). "Several receptors have been found to be upregulated in ovarian cancer tissues, including growth hormone releasing hormone receptor (GHRHR), GRPR, leucine-rich repeat-containing G-protein coupled receptor 5 (LGR5), oxytocin receptor (OXTR) and parathyroid hormone 2 receptor (PTH2R)." (PMID 35625966, 2022).
breast carcinoma (2 papers, 2008 to 2023). "The antagonists of the GHRHR can inhibit proliferation in non-small cell lung cancer and breast cancer." (PMID 36777724, 2023).
congenital hypopituitarism (2 papers, 2022 to 2023). "The authors identified three novel pathogenic variants in GHRHR, OTX2, and GLI2 expanding the spectrum of variants associated with congenital hypopituitarism." (PMID 36288632, 2022).
Obesity (2 papers, 2014 to 2024). Accumulation of substantial excess body fat. "Furthermore, in adipocytes from patients with severe obesity, the expression of GHRHR and GHR is increased compared to patients without obesity." (PMID 39560873, 2024).
prostate tumors (2 papers, 2019 to 2024). "(F) The correlation between RNA levels of GREB1, GHRHR and KLF8 and AR score in 333 TCGA primary prostate tumors were analyzed using Pearson’s correlation analysis (r)." (PMID 30644358, 2019). "Specifically, we found a statistically significant positive correlation (r) between GREB1 RNA level and AR output score across the primary prostate tumors from the TCGA dataset, but not GHRHR or KLF8." (PMID 30644358, 2019).
adolescent idiopathic scoliosis (1 paper, 2020). A scoliosis with no known cause arising in adolescent. "Based on the results in GWAS catalog, the genetic variants of GHRHR associated with congenital left sided heart lesions and adolescent idiopathic scoliosis." (PMID 32934756, 2020).
adrenocortical tumors (1 paper, 2020). "explored the expression of splice variants of growth hormone-releasing hormone receptor (GHRH-R) in human primary adrenocortical tumors and found that splice variants might be a key pathogenic factor in adrenal carcinogenesis." (PMID 32217810, 2020).
atherosclerosis (1 paper, 2014). A disease characterized by the build-up of fatty material and calcium deposition in the arterial wall resulting in partial or complete occlusion of the arterial lumen. "Information on other cardiovascular risk factors in IGHD is scarce, but no premature atherosclerosis signs have been found in untreated type IB patients due to GHRHR mutations in a Brazilian kindred." (PMID 24683479, 2014).
bipolar disorder (1 paper, 2024). A disorder of the brain that causes unusual shifts in mood, energy, activity levels and the ability to carry out day-to-day tasks. "Bipolar disorder, schizophrenia and major depression shared two DEGs: PRDX6 (Peroxiredoxin 6) and GHRHR (Growth-hormone-releasing hormone receptor)." (PMID 39727940, 2024).
cardiomyopathies (1 paper, 2025). "Based on the compelling evidence for the role of GHRHR signaling in cardiac repair, GHRH/GHRH analogs are promising therapeutic candidates for multiple cardiomyopathies and further clinical translational research is needed." (PMID 39883351, 2025).
colorectal cancer (1 paper, 2016). A primary or metastatic malignant neoplasm that affects the colon or rectum. "Subsequently, we screened four genes (ALOX15, GHRHR, TFPI2 and TKTL1) with aberrant methylation and aberrant hydroxymethylation at some genome position by functional enrichment analysis as candidate genes associated with colorectal cancer." (PMID 27546520, 2016).
diabetic retinopathy (1 paper, 2022). "Previous studies have identified several candidate genes associated with the progression of diabetic retinopathy; examples of such candidate genes that were selected in our studies and found to be associated with diabetic retinopathy are GRB2, GHRHR, BMP2, and GAPDH." (PMID 36360284, 2022).
experimental autoimmune encephalomyelitis (1 paper, 2023). An autoimmune demyelinating disease of the central nervous system that is produced experimentally in animals by the injection of homogenized brain or spinal cord in Freund's adjuvant. "Previously growth hormone releasing hormone receptor (GHRH-R) deficient mice have been reported to be less susceptible to the induction of experimental autoimmune encephalomyelitis." (PMID 37280225, 2023).
glaucoma (1 paper, 2026). Increased pressure in the eyeball due to obstruction of the outflow of aqueous humor. "In this study, a dual role for growth hormone-releasing hormone receptor (GHRHR) modulation under glaucoma-relevant conditions and complementary injury paradigms involving the RGCs is identified." (PMID 41849678, 2026).
growth disorders (1 paper, 2020). "Seventeen mutations have been reported in GHRHR, and these mutations will lead to severe growth disorders in patients." (PMID 33076416, 2020).
Insulin resistance (1 paper, 2021). Increased resistance towards insulin, that is, diminished effectiveness of insulin in reducing blood glucose levels. "This defense mechanism against insulin resistance could be realized through the receptors G-protein-coupled receptor (GPCR), growth hormone secretagogue receptor (GHSR), and growth hormone-releasing hormone receptor (GHRHR)." (PMID 33959145, 2021).
isolated growth hormone deficiency (1 paper, 2018). "Congenital isolated growth hormone deficiency (IGHD) type 1b is an autosomal recessive genetic condition caused by mutations of growth hormone (GH)-1 or the growth hormone releasing hormone receptor (GHRH-R) genes." (PMID 29537382, 2018).
prolactinoma (1 paper, 2022). "GHRHR, encoding the receptor for GH-releasing hormone was also upregulated to a lower level but specifically in the M6 prolactinoma." (PMID 35978432, 2022).
skin cancer (1 paper, 2021). "Although both GHRHR and SV1 are present in prostatic, breast, gastric, ovarian, pancreatic, lung, esophageal, oral, and skin cancers, SV1 possess stronger mitogenic activities." (PMID 34599099, 2021).
somatotropinomas (1 paper, 2018). "As expected, GH-releasing hormone receptor (GHRHR) and ghrelin receptor (GHSR1a) were also expressed at high levels in these somatotropinomas (100% and 92% of the cases, respectively), being GHRH-R mRNA levels significantly higher than those of GHSR1a." (PMID 29670116, 2018).
type 2 diabetes (1 paper, 2016). "We also consider the hypothesis that novel GHRHR agonists can improve glucose metabolism in Type 2 diabetes by preserving the function and survival of pancreatic beta-cells." (PMID 27777568, 2016). "There was upregulation of GHRHR expression in intestinal cells in a mouse model of type 2 diabetes." (PMID 27777568, 2016).
cancer (25 papers, 2008 to 2025). A tumor composed of atypical neoplastic, often pleomorphic cells that invade other tissues. "In the Gene Expression Profiling Interactive Analysis database (gepia.cancer-pku.cn), GHRHR mRNA also appeared to be slightly higher in PCa compared to normal tissue." (PMID 40427140, 2025). "GHRHR antagonists strongly augment apoptosis and decrease proliferation of multiple types of cancer cells in vitro and in vivo." (PMID 39934495, 2025). "In the Oncomine cancer microarray database (shut down 17 January 2022), GHRHR mRNA had a 1.65-fold higher expression in PCa compared to normal tissue (LaTulippe Prostate Statistics)." (PMID 40427140, 2025). "GHRHAnt oppose the growth factor activities of GHRH in malignancies and suppress cancers by blocking GHRHR/SVs activation." (PMID 38895505, 2024). "A recent study demonstrates that alternative splicing of GHRHR, promoted by hypoxic microenvironment in solid tumors, is actually a cellular adaptation mechanism that induces cancer cell proliferation and migration." (PMID 34599099, 2021). "However, the expression analysis showed high overexpression of PRLR and GHRHR, both of these receptors representing known targets for chemotherapy in cancer." (PMID 35978432, 2022). "Both GHRH and GHRHR are present in lung, mammary, ovarian, endometrial, gastric, colorectal, ocular, prostatic, and pancreatic cancers." (PMID 34599099, 2021). "Previous studies showed that GHRHR SV1 was expressed in different cancer cells." (PMID 20509930, 2010). "Previous studies showed that SV1 of GHRHR expressed in several cancers, may mediate the direct inhibitory effect of GHRH antagonists." (PMID 20509930, 2010). "Indeed, peptide GHRHR antagonistshave displayed promising results in many cancer models." (PMID 39207455, 2024). "As a splice variant of GHRHR, SV1 only differs by 89 amino acids at its N terminus but causes a distinct biased signaling that may involve a complex regulatory mechanism associated with cancer development." (PMID 34599099, 2021). "Although splice variants of many GPCRs, such as growth hormone–releasing hormone receptor (GHRHR), thromboxane receptor, cholecystokinin-B receptor, secretin receptors, and somatostatin receptor, have been detected in various cancers, their biological significance is poorly understood." (PMID 34599099, 2021). "GHRH and its receptor GHRHR (a member of the G protein-coupled receptor [GPCR] family) are also produced in multiple tissues and cancers to modulate cell proliferation and apoptosis, including PCa." (PMID 40427140, 2025). "SSTR2-SST is also one of the axes with the strongest literature support for a role in cancer, along with several others, including MC1R-POMC and GHRHR-GHRH." (PMID 38723607, 2024). "While the primary role of GHRHR is to stimulate growth hormone synthesis and secretion from the anterior pituitary somatotrophs upon GHRH binding, its ectopic expression in cancers has been studied extensively." (PMID 34599099, 2021). "Due to its physical presence and bioactivity in cancer progression, SV1 is also called tumoral GHRHR that coexists with pituitary GHRHR in most tumors." (PMID 34599099, 2021). "The cancer cell growth could be stimulated by exogenous GHRH and, conversely, inhibited by GHRHR antagonists." (PMID 34599099, 2021). "Here, we examined the expression of GHRHR SV1 in SKOV3 and CaOV3 cancer cell lines." (PMID 20509930, 2010).
tumor (16 papers, 2016 to 2025). "Therefore, modification of GHRHR by splicing at the N terminus results in biased arrestin signaling that might be advantageous to tumor cells." (PMID 34599099, 2021).
GHRHR also shares sentences with these, for which no sentence is quoted: Hypoglycemia (6 papers); acromegaly (5); pituitary tumor (3); pulmonary fibrosis (3); acute myeloid leukemia (2); cervical cancer (2); glioblastoma (2); hypopituitarism (2); inflammation (2); lipodystrophy (2); lung disease (2); non-small cell lung carcinoma (2); pituitary adenoma (2); rectal cancer (2); rectal tumor (2); small cell lung carcinoma (2); somatotroph adenoma (2); acute lymphoblastic leukemia (1); adenoma (1); Apocrine carcinomas (1); autoimmune disease (1); autoimmune uveitis (1); benign tumor (1); Breast Tumors (1); bronchogenic carcinoma (1); central obesity (1); diabetic nephropathy (1); dyslipidemia (1); endometrial cancer (1); epilepsy (1).
A further 37 diseases each share a sentence with GHRHR in 1 paper.